MIR3612 (microRNA 3612)
Synonyms: hsa-mir-3612
Gene: MicroRNA gene on chromosome 12 (128,294,092 to 128,294,178, forward strand). Ensembl gene ENSG00000265635.
Diseases named in the same sentence as MIR3612 in open-access papers:
MIR3612 is named in the same sentence as 1 disease in open-access papers, as found by Europe PMC text mining. Sharing a sentence is not in itself a finding about the gene and the disease.
MIR3612 shares sentences with these, for which no sentence is quoted: infection (1 paper).